HTR2B (5-hydroxytryptamine receptor 2B)
Diseases named in the same sentence as HTR2B in open-access papers (continued):
Sharing a sentence is not in itself a finding about the gene and the disease.
Glucose intolerance (4 papers, 2014 to 2023). Glucose intolerance (GI) can be defined as dysglycemia that comprises both prediabetes and diabetes. "Serotonin participates in beta cell adaptation, acting downstream of the prolactin pathway; the blocking of serotonin receptor B (HTR2B) signaling in pregnant mice impaired beta cell expansion and caused glucose intolerance." (PMID 37480094, 2023). "Factors that reduce serotonin synthesis and perturb HTR2B signaling are associated with decreased β-cell number, impaired insulin secretion, and gestational glucose intolerance in mice." (PMID 33772108, 2021). "In pregnant mice, the HTR2B expression closely matched the period of increased beta cell proliferation and blocking HTR2B signaling impaired beta cell expansion, causing glucose intolerance." (PMID 37480094, 2023). "We hypothesized that the glucose intolerance in our vitamin B6-deficient mice was causatively associated with perturbed HTR2B signaling and that treatment with an HTR2B agonist would promote β-cell proliferation, ultimately improving glucose tolerance." (PMID 33772108, 2021). "Interestingly, treating vitamin B6-deficient dams with an HTR2B agonist increased β-cell proliferation and improved gestational glucose intolerance, suggesting that vitamin B6-induced glucose intolerance is causatively linked to HTR2B activation." (PMID 33772108, 2021). "Female Htr2b knockout mice (Htr2b−/−) develop a moderate glucose intolerance and exhibit reduced β-cell mass, as well as a decreased β-cell proliferation during gestation." (PMID 36983056, 2023). "Moreover, inhibition of Tph1 or Htr2b blocked normal increase of β-cell mass during pregnancy and resulted in glucose intolerance in mice." (PMID 24337628, 2014).
liver fibrosis (4 papers, 2018 to 2026). "The antagonist of Htr2b significantly inhibited the deposition of both Collagen I and Laminin, while the agonist treatment slightly stimulated the progression of liver fibrosis." (PMID 29855567, 2018). "Interestingly, MK-212, an HTR2B agonist, showed a negative liver fibrosis gene expression profile suggesting potential as an anti-fibrotic agent, although formal experimental testing is needed." (PMID 30923657, 2019). "Among the target genes corresponding to these compounds, we found that HTR2B, ABCB1, and ALOX5 were significantly up-regulated in HBV and HCV related liver fibrosis datasets (Data not show)." (PMID 30923657, 2019).
pancreatic cancer (4 papers, 2021 to 2024). "5-HT and HTR2B agonists promote cell proliferation and inhibit cell apoptosis in vitro, with silenced HTR2B blocking tumor growth in vivo, making it a potential drug target for pancreatic cancer treatment." (PMID 38462620, 2024). "High levels of IDO, TPH1, HTR2B, AhR, and Kyn predict a poor prognosis in pancreatic cancer, whereas MAOA expression is negatively correlated with TNM stage and tumor size in pancreatic cancer, predicting a favorable prognosis." (PMID 38462620, 2024). "Among them, LI, the author with the most publications, stated in his magnum opus that the high expression of 5-HT and its receptor HTR2B would increase tumor glycolysis and promote the growth of pancreatic cancer (cited 140 times)." (PMID 36505775, 2022).
heart failure (3 papers, 2012 to 2022). Inability of the heart to pump blood at an adequate rate to meet tissue metabolic requirements. "As a 5-HT receptor, HTR2B activation significantly participates in cardiac remodeling as well as heart failure development and progression." (PMID 35966550, 2022).
Hepatic steatosis (3 papers, 2018 to 2022). Steatosis is a term used to denote lipid accumulation within hepatocytes. "Here, we show that Htr2a (a gene involved in hepatic steatosis) and Htr2b (a gene activated in PH models) are needed for liver regeneration." (PMID 35765850, 2022). "Importantly, these results are supported by the expression of tissue-specific HTRs, such as HTR1B, HTR2A, HTR2B and HTR7, in the liver, the relationship of HTR2A with hepatic steatosis and that of HTR2B with hepatocyte proliferation." (PMID 35765850, 2022). "GDS directly promoted the development and progression of NASH by hepatic HTR2A, rather than HTR2B or HTR2C, those similar to hepatic steatosis was ameliorated with liver-specific Htr2a knockout and the deletion of GDS." (PMID 32477107, 2020).
hepatocellular carcinoma (3 papers, 2021 to 2025). A malignant tumor that arises from hepatocytes. "Interestingly, HTR2B has been described as an oncogene in hepatocellular carcinoma (HCC), prostate, small intestine and breast cancers, but as a tumor suppressor in ovarian cancer." (PMID 35163491, 2022).
liver cancer (3 papers, 2018 to 2024). An epithelial or non-epithelial malignant neoplasm that arises from the liver. "Research showed that 32% and 35% of liver cancer patients had HTR1B and HTR2B expression, respectively, both of which were linked to higher cell growth." (PMID 39766808, 2024). "Furthermore, we demonstrated that inhibition of HTr1B and HTr2B reduced serotonin-mediated cell steatosis since these receptors are involved in liver cancer cell proliferation and tumor development." (PMID 30409162, 2018).
Obesity (3 papers, 2021 to 2024). Accumulation of substantial excess body fat. "HTR2B expression levels are elevated within VAT in people with obesity, and selective HTR2B antagonists may attenuate the inflammatory response in VAT and obesity-associated IR." (PMID 39456156, 2024).
osteoarthritis (3 papers, 2021 to 2026). A noninflammatory degenerative joint disease occurring chiefly in older persons, characterized by degeneration of the articular cartilage, hypertrophy of bone at the margins and changes in the synovial membrane. "A recent research shows that HTR2B are specific markers in age-related osteoarthritis and involved in apoptosis and inflammation of osteoarthritis synovial cells." (PMID 36249530, 2022).
Hyperglycemia (2 papers, 2019 to 2020). An increased concentration of glucose in the blood. "Treatment with the selective htr2b antagonist SB204741 suppressed the hyperglycemia in either db/db mice or KKAy mice." (PMID 33364514, 2020). "In summary, the present findings suggest that expression of the hepatic htr2b is increased in young diabetic db/db mice and KKAy mice, and pharmacologic inhibition of htr2b ameliorates the hyperglycemia and altered expression of hepatic FGF21, Sdf2l1 and htr2a in these mice." (PMID 33364514, 2020). "Moreover, treatment with the selective htr2b antagonist SB204741 suppressed hyperglycemia in db/db mice and KKAy mice without reducing body weight." (PMID 33364514, 2020).
Insulin resistance (2 papers, 2023 to 2025). Increased resistance towards insulin, that is, diminished effectiveness of insulin in reducing blood glucose levels. "Our results suggest that Htr2b inhibition mitigates these detrimental effects, potentially reversing insulin resistance associated with muscle lipid overload." (PMID 40451926, 2025). "To explore the role of Htr2b in the development of insulin resistance and myosteatosis, we generated muscle-specific HTR2b-KO (HTR2b MKO) mice." (PMID 40451926, 2025). "We hypothesize that 5-HT inhibition could restore normal insulin signaling and glucose uptake in skeletal muscles through the 5-HT receptor 2b (Htr2b), thereby alleviating obesity-induced insulin resistance." (PMID 40451926, 2025). "In addition to the negative effect on BAT activity that we describe, peripheral serotonin increases hepatic gluconeogenesis and WAT lipolysis through the 5-HT2B receptor in mice, whereas adipose-specific deletion of Htr2b protects against insulin resistance and hepatic steatosis." (PMID 37537371, 2023).
Myocardial fibrosis (2 papers, 2022 to 2024). "By impairing the deposition of collagen, blockage of HTR2B can suppress myocardial fibrosis." (PMID 35966550, 2022). "The 5-HT-induced myocardial fibrosis was increased in Htr2b null mice but not in Htr2a null or Htr2a/2b double null mice." (PMID 39423037, 2024).
ovarian carcinoma (2 papers, 2014 to 2025). A malignant neoplasm originating from the surface ovarian epithelium. "As stable MALAT1 knockout in lung cancer cells up-regulates HTR2B expression and silencing of HTR2B is a marker for ovarian tumor metastasis in ovarian cancer patients, we propose that repression of HTR2B expression contributes to MALAT1-mediated tumor cell migration, invasion and metastasis." (PMID 24742640, 2014).
Stroke (2 papers, 2012 to 2016). Sudden impairment of blood flow to a part of the brain due to occlusion or rupture of an artery to the brain. "Treatment with fluoxetine attenuated the expression of Htr2B mRNA, stimulated post-stroke neurogenesis in the subventricular zone and was associated with an improved anhedonic behavior and an increased activity in the forced swim test in aged animals." (PMID 27013593, 2016). "We hypothesize that HTR2B expression in the infarcted territory may render degenerating neurons susceptible to attack by activated microglia and thus aggravate the consequences of stroke." (PMID 27013593, 2016). "Although the mRNA expression was largely down-regulated by day 14 post-stroke, the HTR2B/NeuN protein co-localization persisted in the peri-infarcted area (arrows)." (PMID 27013593, 2016). "Despite persistent expression of Iba1 in the peri-infarcted territory (inset), the co-localization between Iba1 and HtR2B was less evident by day 14 after stroke in aged animals." (PMID 27013593, 2016). "We found that HTR2B-positive cells were co-localized with NeuN-positive nuclei at day3 after stroke in aged rat brains (arrows)." (PMID 27013593, 2016). "In aged rats, however, a co-localization of the microglia marker Iba1 with HTR2B-expressing neurons and blood vessels (Bv) was seen at day 3 post stroke." (PMID 27013593, 2016). "Of these Cort, which is also involved in sleep homeostasis remained downregulated on day14 post-stroke in both age groups, and Acvr1c, Htr2b and Fstl1 all involved in pain response, remained high at day14 in aged rats." (PMID 23251410, 2012). "Of the genes possibly involved in post-stroke depression, we found by transcriptomics analysis using the Affymetrix platform, that the transcripts encoding the serotonin receptor 2B (Htr2b) but not Htr2a were upregulated after stroke in the aged rat stroke model." (PMID 27013593, 2016).
aortic stenosis (1 paper, 2020). Aortic valve stenosis is a aortic valve disease caused by the incomplete opening of the aortic valve. "We found that genetic mutation of the 5-HT2B receptor–via Htr2b deletion–mitigates hemodynamic progression of aortic stenosis." (PMID 33237915, 2020).
aortic valve stenosis (1 paper, 2020). Aortic valve stenosis (AVS) is a condition characterized by narrowing of the heart's aortic valve opening. "Htr2b mutant mice showed lower aortic valve peak velocity and mean pressure gradient–classical hemodynamic indicators of aortic valve stenosis–without concurrent left ventricle change." (PMID 33237915, 2020).
calcific aortic valve disease (1 paper, 2020). "Thus, the objective of this study was to determine if genetic ablation or pharmacological antagonism of the 5-HT2B serotonin receptor (gene: Htr2b) could improve the hemodynamic and histological progression of calcific aortic valve disease." (PMID 33237915, 2020).
cognitive deficits (1 paper, 2023). "HTR2B knock-out mice also exhibit an antipsychotic-sensitive behavioral phenotype reminiscent of SCHIZ, including decreased pre-pulse inhibition, dysfunctional social interaction, and cognitive deficits." (PMID 37031222, 2023).
diabetes (1 paper, 2017). "The mRNA level of Htr2b was detected at low level in islets of WT mice, but its level was around 3 fold higher in islets of db/db mice, suggesting that Htr2b may be implicated in decreased GSIS in this diabetes mouse model." (PMID 28129327, 2017). "Interestingly, in islets of db/db mice, a model of diabetes and β-cells dysfunction, the mRNA level of Htr2b was ∼3-fold higher compared to islets of WT mice." (PMID 28129327, 2017).
dilated cardiomyopathy (1 paper, 2022). Cardiomyopathy which is characterized by dilation and contractile dysfunction of the left and right ventricles. "Moreover, HTR2B deficiency can cause dilated cardiomyopathy or myofibrillar breakdown." (PMID 37551283, 2022).
ductal breast carcinoma in situ (1 paper, 2023). A carcinoma entirely confined to the mammary ducts. "HTR2B was found overexpressed in ductal breast carcinoma in situ stroma (FC = 2.185) and invasive breast carcinoma stroma compared to normal samples (FC = 3.648)." (PMID 37795441, 2023).
gastritis (1 paper, 2025). Inflammation of the stomach. "HTR1A was upregulated in the stomachs of mice chronically infected with H. pylori SS1 (3 weeks) compared to uninfected controls, whereas HTR2B was upregulated only in acutely infected mice (3 days), consistent with a role for 5-HT signalling in the development of gastritis." (PMID 40869057, 2025).
invasive ductal breast carcinoma (1 paper, 2023). The most common type of invasive breast carcinoma, accounting for approximately 70% of breast carcinomas. "Nevertheless, it was showed that HTR2B was downregulated in invasive ductal breast carcinoma with a FC of 2.567 (The Radvanyi Breast Statistics), intraductal cribriform breast adenocarcinoma with a FC of 4.579 and mucinous breast carcinoma with a FC of 2.455 (TCGA breast statistics)." (PMID 37795441, 2023).
irritable bowel syndrome (1 paper, 2024). Irritable bowel syndrome (IBS) is a chronic functional condition of the lower gastrointestinal (GI) tract characterized by abdominal pain or discomfort and disordered bowel habit (diarrhea, constipation, or fluctuation between the two). "Tegaserod and alosetron were initially used to treat irritable bowel syndrome, but they have been withdrawn due to cardiovascular complications associated with off-targets HTR1A and HTR2B, as inferred by our model." (PMID 39570605, 2024).
ischemia (1 paper, 2018). A hypoperfusion of the BLOOD through an organ or tissue caused by a PATHOLOGIC CONSTRICTION or obstruction of its BLOOD VESSELS, or an absence of BLOOD CIRCULATION. "We hypothesize that MCAO could induce Htr2a and Htr2b overexpression leading to excitability in the early stage of ischemia." (PMID 30533429, 2018).
left ventricular dilation (1 paper, 2024). "In surviving adult Htr2b null mice, echocardiography confirmed the presence of left ventricular dilation and decreased systolic function." (PMID 39423037, 2024).
liver diseases (1 paper, 2022). "Among the various subtypes of HTRs expressed by hepatocytes, HTR2A and HTR2B show a strong relationship to liver diseases as they transduce the 5-HT signal from the SI via the portal vein." (PMID 35765850, 2022).
metastatic disease (1 paper, 2018). "One particular characteristic that is clearly becoming a discriminating mark in order to identify those primary UM tumors at risk of progressing toward the metastatic disease is the detection of high levels of the HTR2B mRNA transcript." (PMID 30347896, 2018). "The human gene encoding the 5-Hydroxytryptamine receptor 2B (HTR2B), also known as the serotonin receptor 2B, turn out to be the most discriminating among the class II genes in order to identify UM patients at high risk of evolving toward the liver metastatic disease." (PMID 30347896, 2018).
morbid obesity (1 paper, 2020). An excess of body weight, normally defined as an individual with a body mass index greater than 35 or a body weight greater than one hundred percent of ideal body weight. "Although our cohort made it possible to establish a clear relationship between women with morbid obesity and NAFLD with deregulated hepatic HTR2B expression, these results cannot be extrapolated to overweight subjects." (PMID 33081272, 2020).
neuroblastoma (1 paper, 2014). Neuroblastoma (NB) is the most common solid, extracranial childhood tumor. "RT-PCR studies confirmed that transfection with JMJD1A siRNA-1, JMJD1A siRNA-2, N-Myc siRNA-1 or N-Myc siRNA-2 significantly increased FAM73A and HTR2B mRNA expression in neuroblastoma cells." (PMID 24742640, 2014).
osteosarcoma (1 paper, 2025). A usually aggressive malignant bone-forming mesenchymal neoplasm, predominantly affecting adolescents and young adults. "The investigation demonstrates that HTR2B is downregulated in osteosarcoma tissues, and correlates with poorer survival outcomes." (PMID 40387572, 2025). "In summary, our study identifies HTR2B as a critical tumor suppressor in osteosarcoma progression, functioning through the NLRP3 inflammasome pathway." (PMID 40387572, 2025). "Activation of HTR2B suppresses osteosarcoma progression through the STAT1‐NLRP3 inflammasome pathway and promotes OASL1+ Macrophage production to enhance anti‐tumor immunity." (PMID 40387572, 2025). "Our study identified HTR2B as a potential prognostic biomarker and explores its role in osteosarcoma progression, offering new insights into its therapeutic potential." (PMID 40387572, 2025). "Transwell assay further revealed that HTR2B overexpression diminished both migration and invasion capabilities of osteosarcoma cells." (PMID 40387572, 2025). "The HE staining confirmed the presence of osteosarcoma tumor tissues, the immunohistochemical staining revealed increased HTR2B expression, and decreased Ki67 levels in the OE‐HTR2B group." (PMID 40387572, 2025). "Having confirmed the detrimental effect of HTR2B and STAT1 on osteosarcoma, we focused on discovering the underlying molecular mechanisms." (PMID 40387572, 2025). "The GSE19276 dataset revealed that HTR2B is downregulated in osteosarcoma tissues compared to normal tissues." (PMID 40387572, 2025). "HE staining confirmed the presence of osteosarcoma tumor tissues, IHC revealed increased HTR2B expression and reduced Ki67 levels in the BW‐723C86‐treated group." (PMID 40387572, 2025). "Therefore, NLRP3‐inflammasome may be the underlying molecular mechanism of HTR2B in osteosarcoma." (PMID 40387572, 2025). "Upregulating HTR2B through lentiviral‐mediated gene delivery or the agonist BW‐723C86, resulted in a marked suppression of osteosarcoma cell progression via the STAT1‐NLRP3 inflammasome pathway." (PMID 40387572, 2025). "Lentivirus and agonist BW‐723C86 are employed to assess HTR2B overexpression effects in osteosarcoma cell lines." (PMID 40387572, 2025). "Survival analysis was conducted in osteosarcoma samples, and reinforcing the prognostic significance of low HTR2B expression as an indicator of adverse survival in osteosarcoma patients." (PMID 40387572, 2025). "Additionally, the classification diagrams of T cells, B cells, NK cells, DC types found that overexpression of HTR2B can enhance antitumor immunity in osteosarcoma tumor microenvironment." (PMID 40387572, 2025). "Additionally, high expression of HTR2B associated with high StromalScore, ImmuneScore, and ESTIMATEScore, and low TumorPurify both in GSE19276 and TARGET‐Osteosarcoma databases." (PMID 40387572, 2025). "This study aims to explore the potential roles of HTR2B in osteosarcoma progression." (PMID 40387572, 2025). "Protein–protein interaction analysis suggested that STAT1 may be a potential downstream‐acting molecule of HTR2B activation suppresses osteosarcoma progression." (PMID 40387572, 2025). "HTR2B expression is analyzed using the TARGET, GEO databases, and osteosarcoma tissue samples in the hospital." (PMID 40387572, 2025). "Moreover, the relationships between HTR2B and immune cell analysis demonstrated that high expression of HTR2B correlated with elevated macrophage levels in the GSE19276 and TARGET‐Osteosarcoma databases." (PMID 40387572, 2025). "Moreover, Combined the overexpression of HTR2B and knockdown of STAT1 can further suppresses osteosarcoma progression via NLRP3 inflammasome." (PMID 40387572, 2025).